CDH11 (cadherin 11)
Diseases named in the same sentence as CDH11 in open-access papers (continued):
Sharing a sentence is not in itself a finding about the gene and the disease.
tumor (continued). "Thus, our findings that CDH11 KD cells showed no change in cell proliferation in vitro but were suppressed in vivo suggest that CDH11‐mediated cell–cell interactions between tumor cells and other cell types in the surrounding microenvironment are required for tumor growth in BC." (PMID 41263259, 2025). "Consequently, from the intricate relationships between CDH11 expression and the infiltration of multiple immune cells, we speculate that the interactions between the tumor microenvironment and CDH11 played key roles in the oncogenic influence of CDH11 in OSCC." (PMID 37013637, 2023). "Therefore, enzymatic treatment could be recapitulating key aspects of the tumor microenvironment and its influence on CDH11 localization leading to nuclear accumulation of CDH11 as observed in clinical TMA samples." (PMID 37558205, 2023). "Finally, our results may provide novel ways to reduce tumor growth and metastatic potential by inhibiting CDH11 proteolytic degradation and subsequent translocation of β‐catenin to the nucleus." (PMID 37558205, 2023). "Therefore, CDH11 likely plays a vital role in tumor immune escape and could provide a prognostic biomarker and potential therapeutic target for patients with GC." (PMID 32685527, 2020). "Thus, CDH11 in tumor cells plays important roles in suppressing proliferation and invasion." (PMID 30828336, 2019). "However, tumor growth was faster in Cdh11-null mice between PND8 and PND84 (p = 0.003)." (PMID 20421947, 2010). "We further present a visualization of gene expression dynamics for MYB, CD24, CDH11, and VIM along with the spatial pseudotime trajectory, highlighting the progressive transcriptional shifts asso1ciated with tumor progression and EMT56." (PMID 40950184, 2025). "Residing on 16q are many notable tumor suppressor genes including LC3B, CYLD, CDH11, CDH1, ZFHX3, CREB, CTCP, and all metallothioneins (MTs), which emerging research indicates are also tumor suppressors." (PMID 40565600, 2025). "To assess CDH11 protein expression in human tumors from various anatomical locations, we employed a tissue microarray (TMA) containing 209 primary tumor clinical samples and immunostained for the intracellular domain of CDH11." (PMID 37558205, 2023). "Of the 11 neoplasm-related genes in these subclusters, the expression of six (ANGPT2, TP73, NOVA1, CDH11, CXCL12, and LAMA1) were significantly repressed in KRT and one (EPHA2) was higher expressed in KRT compared with IMU." (PMID 37654626, 2023). "The mesenchymal markers ACTA2, CDH2, CDH11, and VIM are involved in proliferation, generation of stem-cell-like cells, and tumor progression." (PMID 37345150, 2023). "Cadherin 11 (Cdh11), a cell-to-cell adhesion molecule, has been suggested to promote tumor growth and immunosuppression in PDAC, and Cdh11 inhibition significantly extended survival in mice with PDAC." (PMID 37954069, 2023). "However, the mechanism through which CDH11 may affect tumor growth and metastasis remains elusive." (PMID 37558205, 2023). "For example, among 10 markers that are localized in the tumor stroma according to IHC images, 4 genes (MFAP2, MFAP5, PDGFRA, CDH11) are specifically represented in “Fibroblasts”, while the remaining markers are expressed in both cell types." (PMID 36263012, 2022). "Our volcano plot and GO analysis showed the significant downregulation of tumor-suppressive genes, such as ANOS1, CDH11, COL4A5, POSTN, PTN, and BEX1 in As- transformed cells, which is considered an early event of carcinogenesis." (PMID 35954277, 2022). "Together with the altered CSF2, the two cell adhesion proteins, osteoblast-cadherin (CDH11) and N-cadherin (CDH2) were downregulated, suggesting that osteoclasts decrease the tumor cell ability to adhere to mesenchymal cells in the microenvironment." (PMID 35971022, 2022).
tumor (continued). "CDH11 can induce cell periodic arrest and apoptosis in G0 or G1 phase, inhibit the proliferation of CRC cells and formation of colonies, and inhibit tumor cell growth, migration, invasion and proliferation by inactivating NF-κB signal pathway." (PMID 33442417, 2021). "Here, we reported that CDH11 not only promotes the biological process of EMT but also is closely related to a poor prognosis in GC patients, especially in those with more severe tumor stages." (PMID 32685527, 2020). "Principal component analysis and random forest analysis were employed to further screen for six hub genes, including ISLR, COL1A2, CDH11, SPARC, COL3A1, and COL1A1, which exhibited a good ability to differentiate between tumor and normal samples." (PMID 32612640, 2020). "CDH11 inhibition suppresses the CSC-like phenotypes and tumor growth of TNBC cells and represents a novel therapeutic approach in TNBC treatment." (PMID 30691241, 2019). "The phenotypes of aggressive RA-FLSs can have tumor-like attributes in terms of excessive proliferation, invasion, and migration capacities, suggesting that suppressing pPDGFRαβ expression and promoting CDH11 expression in FLSs could be an effective treatment strategy for RA." (PMID 30828336, 2019). "To gain mechanistic insight into how TEAD1 regulates tumor migration, we overexpressed AQP4 and CDH11 in sham and TEAD1KO spheroids and studied their migratory behavior." (PMID 30275445, 2018). "When compared to the primary tumor, the expression of some EMT markers, CDH11 and vimentin, is elevated in CTCs, whereas others, S100A4, Itga5, Sdc1, are decreased." (PMID 28544498, 2017). "We confirmed tumor-specific overexpression for three genes (CDH11, ICAM1 and CLDN3) using qRT-PCR, and demonstrated protein localization specific to the cell surface of tumor cells by IHC." (PMID 27363029, 2016). "Tumours originating from CDH11-transfected SIHN011B cells had a significantly lower weight and volume than empty vector-transfected-derived tumours." (PMID 22374749, 2012). "Three million CDH11 shRNA-depleted SIHN011A cells were subcutaneously injected into nude mice; 30 days after injection, all the mice were killed and their tumours weighed." (PMID 22374749, 2012). "Expression of N-cadherin (N-cad) and cadherin-11 (CDH11), the dominant subtypes in normal ovarian surface epithelium, were significantly higher in the benign and LMP tumours of our study than in the adenocarcinomas." (PMID 15471544, 2004). "Finally, the levels of genes involved in the tumor EMT, such as CDH2, CDH11, SMAD2, SMAD3, WNT9A, and SP-1, were significantly downregulated after the SH intervention." (PMID 41444284, 2025). "Next, we investigated how the lack of Cdh11 in the stroma impacts the tumor immune microenvironment." (PMID 37954069, 2023). "CDH11, COL6A3, EDNRA, and SERPINF1 were all negatively correlated with tumor purity." (PMID 36595851, 2022). "These cells are not transformed so that, unlike tumor cells, the relationship between Src, cadherin-11, and Stat3 can be examined in the absence of confounding pathways." (PMID 35411090, 2022). "Moreover, inhibition of cadherin-11 in the MDA-MB-231 decreased migration, growth in soft agar, stem cell marker expression, and in vivo tumor growth." (PMID 33591483, 2021). "Comparing tumor to parent cell, the cadherins CDH1 and CDH11 were different by −2 and 11.3-fold." (PMID 33808801, 2021). "Cadherin-11 mediated LA-induced collagen expression in CD115(+) precursors, which may participate in collagen deposition in the tumor microenvironment." (PMID 33478523, 2021). "Interestingly, we observed that CDH11 silencing in CAF-S1 prevented this effect and kept the CDH1/E-cadherin protein level elevated at the surface of MCF7 and T47D tumor cells." (PMID 32665033, 2020). "Meanwhile, CDH11 also shows a robust positive correlation with MMP2, which is one of the notable molecules in the MMP family involved in cell adhesion, angiogenesis, and tumor progression." (PMID 32685527, 2020).
tumor (continued). "Using functional assays, we found that inhibition of CDH11 expression in CAF-S1 fibroblasts significantly reduced CDH1/E-cadherin expression in tumor cells and CAF-S1-mediated pro-migratory effects on BC cell lines, thereby highlighting that CDH11 is a new key player in relapse in early luminal BC." (PMID 32665033, 2020). "Under the cooperative regulation of inflammatory factors and cadherin-11, the invasiveness and proliferation of PVNS FLS gradually loses control, eventually promoting the transformation of PVNS from an initial inflammatory disease to neoplastic disease." (PMID 32929367, 2020). "In contrast, CDH11 expression was weak or even undetectable in tumor cells and without any difference between cases and controls." (PMID 32665033, 2020). "This evidence indicates that CDH11 may participate in ECM remodeling and the formation of the tumor immune microenvironment." (PMID 32685527, 2020). "Cadherin-11-mediated inflammation results in PVNS with high recurrence, invasiveness, and strong cartilage destruction ability, and eventually promotes the transformation of PVNS from the initial inflammatory disease to neoplastic disease." (PMID 32929367, 2020). "Corroborating the results above, our IHC data demonstrated that tissues from TNBC patients concurrently overexpressed CDH11 and β-catenin proteins, compared to the weak/non-expression in non-tumor tissues." (PMID 30691241, 2019). "Recently we demonstrated that by modulating β-catenin, CDH11 regulates the canonical WNT signalling pathway, and its inhibition suppresses the CSC-like phenotypes and tumor growth of TNBC cells, making a case for the therapeutic targeting of CDH11 as a novel therapeutic approach in TNBC treatment." (PMID 31248373, 2019). "In addition to the genes discussed, there were additional stromal genes identified by the NN analysis, including CDH11, OLML3, FSTL1, AEBP1, VCAN, previously reported to correlate with tumor progression and metastasis in various cancers." (PMID 27128408, 2016). "The expression of MMP2 and CDH11 in LNCaP-19 and PC-3 in comparison to LNCaP and elevated expression levels of these genes upon OCM stimulation in LNCaP-19, suggests that castration-resistance potentiates the communication between tumor cells and osteoblasts." (PMID 24292404, 2014). "On the contrary, in our experimental set up WA decreased EMT-related components of the TGF-β signaling pathway (TGFA, TGFBR2, CDH11), as well as TGM2, HIF1A, several TNFSF family members and ANGPTL2, which stimulate tumor promoting pro-inflammatory responses and a hypoxic microenvironment." (PMID 24498382, 2014). "Comparing the osteogenic potential between these cell lines, LNCaP-19 exclusively has a basal expression of osteoblast-cadherin (CDH11), collagen 1a1 (COL1A1) and osteopontin (Opn, SPP1), all vital genes for tumor interaction with osteoblasts and osteoblastic activity." (PMID 24292404, 2014). "We observed that CDH11 hypermethylation occurred preferentially in the lymph node metastasis and not in the primary tumour counterpart." (PMID 22374749, 2012). "The DNA methylation microarray data showed that CDH11 had a CpG site located in its 5′-CpG island (−173 bp position) that was hypermethylated in the metastatic cell lines IGR37 and SIHN011B but unmethylated in the primary tumour cell lines IGR39 and SIHN011A." (PMID 22374749, 2012). "Our data indicate that when Cdh11 is lost, cell death is deficient while proliferation remains unchanged, suggesting that the tumor suppressor function of Cdh11 is mediated through promotion of apoptosis rather than inhibition of cell proliferation." (PMID 20421947, 2010). "We performed PCNA staining (a marker of cells in early G1 and S phase) of PND84 tumors in selected sections of Cdh11+/+;TAg+/- (n = 2) and Cdh11-/-; TAg+/- (n = 2) mice and calculated the percent PCNA positive cells per tumor volume revealing little difference between the two genotypes." (PMID 20421947, 2010).
tumor (continued). "Similar to tumor cells, we observed nuclear localization of CDH11‐ID in both mesenchymal cell types, suggesting that CDH11 cleavage and nuclear translocation of CDH11‐ID may not be restricted only to tumor cells." (PMID 37558205, 2023). "Our studies utilized mice that lack Cdh11 since birth and therefore it is unknown if the lack of Cdh11 from birth fundamentally changes fibroblast or any other Cdh11-expressing cells, priming an anti-tumor microenvironment." (PMID 37954069, 2023). "Tumor growth was observed in one lentivirally-infected line approximately one month after inoculation but these cells were found to be re-expressing CDH11 in vitro as measured by Western blot (data not shown)." (PMID 24681547, 2014). "Similarly, the DE of CDH11 between tumor and normal cell lines may be non-significant, unlike in tissues." (PMID 35646642, 2022). "In addition to CDH11, we found differences in the expression of multiple cadherin molecules in GBM vs. normal brain, suggesting that regulation of the overall cadherin cell-adhesion expression landscape may play a crucial role in tumor development." (PMID 23951053, 2013). "We confirmed that three of these candidates (CDH11, ICAM1 and CLDN3) were overexpressed in tumors when compared to normal esophagus, normal gastric and non-dysplastic Barrett's, and localized to the surface of tumor cells." (PMID 27363029, 2016). "The expression of CDH11 was not detectable in the metastatic cell lines IGR37 and SIHN011B, showing CpG island methylation, whilst it was expressed in the unmethylated primary tumour-derived cell lines IGR39 and SIHN011A." (PMID 22374749, 2012).
cancer (96 papers, 2004 to 2025). A tumor composed of atypical neoplastic, often pleomorphic cells that invade other tissues. "The apparent contradiction between the known effects of CDH11 on cancer progression and its association with improved survival in the context of immunotherapy warrants further exploration to clarify its role and mechanism in enhancing immunotherapy efficacy." (PMID 38890392, 2024). "First, non-immune scRNA-seq data was computationally analyzed to determine Cdh11 deficiency-induced changes in cancer and stromal cells." (PMID 37954069, 2023). "Our analysis showed that Cdh11 is expressed primarily in cancer-associated fibroblasts (CAFs) and at low levels in epithelial cells undergoing epithelial-to-mesenchymal transition (EMT)." (PMID 37954069, 2023). "CDH11 is a mesenchymal cadherin that is frequently expressed in many cancers and is associated with aggressive cancer behaviors, such as invasion and migration." (PMID 33391403, 2021). "Epithelial-mesenchymal transition (EMT) is characterised by increased levels of snail, MMP14, cadherin-11 and vimentin and is associated with cancer invasion and metastasis." (PMID 32694700, 2020). "Another important aspect of our results is that CDH11 was found to be strongly linked to the infiltration level of diverse immune cells in different types of cancer, especially GC." (PMID 32685527, 2020). "Both reduced and increased levels of CDH11 are linked to patient survival and reduced metastasis in numerous cancers; however, its role is contrasting in different cancer cell types." (PMID 33192560, 2020). "CDH11 is a mesenchymal cadherin that is frequently expressed in various cancer types in association with aggressive cancer behaviors, such as adhesion, migration, and metastasis." (PMID 31160603, 2019). "Another remarkable common point with NCC migration and invasion during development is the fact that cadherin-11 has also been reported to be overexpressed in several cancers and linked to cell migration and invasion." (PMID 30190671, 2018). "SP-1 was also reported to promote invasion and migration of cancer cells by upregulating expression of the metastasis-associated proteins integrin α5 and cadherin-11." (PMID 28286419, 2017). "Cadherin-11 is expressed in the mesoderm-derived tissues, associated with the epithelial-to-mesenchymal transition, and regulates osteogenesis and cancer metastasis to the bone." (PMID 24618420, 2014). "The level of CDH11 is elevated in various cancers and its expression is closely associated with cancer cell migration and metastasis." (PMID 24810778, 2014). "Together, these findings further confirm the role of Cdh11 in cancer progression and suggest that Cdh11 deficiency in stromal cells may significantly alter the TME." (PMID 37954069, 2023). "CDH11 - Cadherin-11 (CDH11) has been associated with aggressive cancer." (PMID 38304289, 2023). "Furthermore, we showed that in the presence of CDH11-rich cancer-associated fibroblasts (CAFs), MCF7 and MDA-MB-231 MBC cell lines acquired enhanced metastatic phenotype with increased CDH11, β-catenin, vimentin, and fibronectin (FN) expression." (PMID 31248373, 2019). "In addition to these cancers, there are many other cancers that are associated with CDH11." (PMID 33442417, 2021). "Thereby, the promoter CpG island hypermethylation-associated silencing of CDH11 in metastatic cells, as a component of this superfamily, is consistent with the hypothesis that epigenetic inactivation of this gene could further enhance cancer dissemination." (PMID 22374749, 2012). "Then, we assessed the suitability of CDH11 as a potential therapeutic target for SACC and observed its robust expression in SACC, specifically in hybrid EMT cells and cancer‐associated fibroblasts (CAFs)." (PMID 39739317, 2025). "On chromosome 11, 30 SNPs were concentrated in the intergenic region between CDH5 and CDH11, both members of the cadherin family, which are involved in cancer and vascular disease." (PMID 40427243, 2025).